SMARCA2 (SWI/SNF related BAF chromatin remodeling complex subunit ATPase 2)
Diseases named in the same sentence as SMARCA2 in open-access papers (continued):
Sharing a sentence is not in itself a finding about the gene and the disease.
tumor (continued). "Furthermore, the absence of Claudin-4 expression led to the diagnosis of a Mesenteric SMARCA2-deficient yet SMARCA4-preserved undifferentiated tumor." (PMID 40012963, 2025). "Interestingly, only the loss of SMARCA2 was found concomitant with the presence of tumor lepidic components and epidermal growth factor receptor (EGFR) mutations, whereas the loss of SMARCA4 was mutually exclusive with those findings." (PMID 39888726, 2025). "SMARCA2 expression was strongly associated with tumor stage, tumor size, and lymph node metastasis." (PMID 38900084, 2024). "The third one is loss&CN-LOH on 9p (hotspot #11) that may target several tumor suppressors, among them SMARCA2, NFIB and PTPRD." (PMID 38473323, 2024). "We evaluated the loss of SMARC4A and SMARCA2 in this heterogeneous tumor group." (PMID 36178285, 2023). "Also, high expression of SMARCA4 or SMARCA2 is frequently associated with an opposite prognosis in cancer, and their levels correlate inversely with the histologic tumor grade." (PMID 36674511, 2023). "Dual loss of SMARCA4 and SMARCA2 also impacts tumor cell growth in PAX3:FOXO1+ARMS." (PMID 37350942, 2023). "A tumor-suppressive function may be attributed to the association of SMARCA2 with senescence in melanocytic nevi." (PMID 35323214, 2022). "In addition, high levels of SMARCA2 expression were associated with a low tumor stage and well-differentiated tumors in LIHC and KIRC." (PMID 29391527, 2018). "Similarly, in KIRC tumors, high expression of SMARCA4 is associated with increased undifferentiated histological grade, while high levels of SMARCA2 were associated with low tumor stages and well differentiated histology." (PMID 29391527, 2018). "This study emphasises the development of PROTACs that selectively and effectively target SMARCA2 in vivo through the conversion of non‐selective SMARCA2/4‐binding ligands, thereby potentially offering a new therapeutic opportunity for patients with tumours harbouring SMARCA4 mutations." (PMID 39779467, 2025). "A947 is another potent, moderately selective SMARCA2 degrader, which achieves approximately 28‐fold preferential degradation of SMARCA2 with minimal growth inhibition in SMARCA4‐wild‐type tumours." (PMID 41537447, 2026). "In OSCC cells, however, this regenerative switch was uncoupled from Smarca2 depletion due to tumor-specific chromatin state remodeling." (PMID 41756468, 2026). "It recruits an E3 ligase to induce highly selective (>1000‐fold) degradation of SMARCA2 and demonstrates anti‐proliferative activity against SMARCA4‐deficient tumours in vitro and in vivo with good tolerability." (PMID 41537447, 2026). "Previous studies have demonstrated that the core genes of NPC-RSS, including SMARCA2, DMC1, CD9, PSG4, and KNG1, are associated with tumor radiosensitization to varying degrees." (PMID 40530955, 2025). "Histopathologically, in NSCLC (frequently LUAD), NE markers have been observed in tumours deficient in SMARCA4, SMARCA2 and even SMARCB1." (PMID 41025426, 2025). "In this case, downregulated pathwayswere associated with SMARCA2 targets, epigenetic changes, metastasis,AKT targets, Hedgehog signaling, MYC targets, tumor evasion, and livercancer." (PMID 40821580, 2025). "The inverse correlation between the A947 concentrations and transcriptional target gene (KRT80) biomarker representing SMARCA2 levels were demonstrated in tumor tissues." (PMID 38755248, 2024). "The expression of SMARCA2 in tumor tissues was lower than that in normal thyroid tissues, especially in high‐cell tumors." (PMID 38900084, 2024). "In this regard, dosing every 2 weeks at 40 mg/kg still showed sustained tumor growth inhibition that was similar to 40 mg/kg dosed weekly, with comparable effects on the pharmacodynamic biomarkers SMARCA2 and KRT80 mRNA." (PMID 38755248, 2024). "Most recently, a SMARCA2/4 degrader disrupted promoter and enhancer interactions and suppressed tumor growth in prostate xenograft models." (PMID 38472198, 2024).
tumor (continued). "By analyzing different GEO datasets, we also found that SMARCA2 expression was lower in poorly differentiated tumor types." (PMID 38900084, 2024). "Similar to the expression pattern of SETMAR, the expression of SMARCA2 was also reduced in relatively poorly differentiated tumor tissues." (PMID 38900084, 2024). "Additional immunostainings on the primary tumor showed partial loss of SMARCB1 and SMARCA2, and patches of nuclear β-catenin positivity." (PMID 38201285, 2023). "Even epigenetic changes are involved in this tumor biology, such as key mutations in chromatin remodeling (MERC1, SMARCA2, ARID1A, ARID1B, SMARCA4) and an imbalance in miRNAs (miR-155, miR-320a, miR-99a, miR-205) that regulate gene expression." (PMID 37476370, 2023). "Different from the original primary tumor, cell line TCS627 demonstrated loss of SMARCA4 and SMARCA2 in a very large majority of cells, while SMARCB1 expression was completely absent." (PMID 38201285, 2023). "It has been reported that losses of SMARCA4 and SMARCA2, which play a role in the repair and remodeling of chromatin, contribute to the initiation, progression, and differentiation of neoplasms." (PMID 36178285, 2023). "When A947 was administered in SMARCA4-mutant xenograft studies, tumour stasis was again observed despite >95% reduction of SMARCA2 levels in the tumours." (PMID 36720862, 2023). "SMARCA2 protein levels in most compound-treated tumours collected at the end of this study were decreased to background levels." (PMID 36216795, 2022). "Taken together, the data are supportive of a tumor cell intrinsic effect of SMARCA2 degradation and provide pharmacologic support of the synthetic lethal interaction." (PMID 36357397, 2022). "At the end of the study, SMARCA2 levels were undetectable by IHC in most treated tumour samples from both treatment groups." (PMID 36216795, 2022). "Both SMARCA4 and its paralog, SMARCA2, are identified as tumor suppressors or drivers of cancer and emerging therapeutic approaches are targeting these genes." (PMID 35626007, 2022). "A slight rebound in SMARCA2 protein levels was observed over the 14 day period as tumor concentrations of A947 decreased; however due to prolonged A947 tumor exposures, these concentrations never reached baseline levels." (PMID 36357397, 2022). "We tested compound 11 in an NCI-H1568 xenograft study, treating mice orally with 100 mg/kg, and evaluated SMARCA2 levels in viable tumour tissue 48 h after treatment." (PMID 36216795, 2022). "miR-199a-3p can induce metastasis of malignant tumor cells by inhibiting the expression of SMARCA2, downregulating the expression of SMARCA4, and inhibiting the expression of TGF-β." (PMID 35342417, 2022). "The expression of most BrD members significantly negatively correlated with cancer stemness across many TCGA tumor types, although only for KAT2B, KMT2A, SMARCA2, BAZ2B, SP100 and SP140, the association was highly consistent (regardless of the tumor type)." (PMID 35049055, 2022). "These tumor have a distinctive IHC profile (loss of SMARCA4/BRG1, loss of SMARCA2/BRM, and expression of stem-cell markers SALL4, CD34, SOX2), although SOX2 is also commonly positive in NECs." (PMID 34663914, 2022). "In tumour samples collected at the end of the study, compound 6 treatment resulted in undetectable levels of SMARCA2 as assessed by IHC." (PMID 36216795, 2022). "A947 treatment led to more than a 95% decrease in tumor SMARCA2 protein levels in both models, however a slightly stronger suppression of KRT80 transcript was observed in the HCC515 model." (PMID 36357397, 2022). "Nevertheless, it is notable that despite efficient degradation of SMARCA2 in vivo, only tumour stasis was observed upon compound treatment in the models studied herein." (PMID 36216795, 2022). "The IV administration of A947 resulted in rapid reduction (96% reduction by 4 h) in tumor SMARCA2 protein levels and achieved a maximal reduction by 24 h." (PMID 36357397, 2022).
tumor (continued). "This also raises the possibility to avoid the loss of SMARCA2 in SCCOHT using inhibitors of ATPase/Bromodomain, since the cell line survival is dependent on the SMARCA2 loss in a SMARCA4-deficient tumor." (PMID 34440689, 2021). "We were able to demonstrate loss of SMARCA2 expression and mutations characteristic of an SWI/SNF-deficient carcinoma in a tumor derived from the gallbladder." (PMID 34118935, 2021). "The ability of SMARCA2 to compensate for the loss of SMARCA4 has made SMARCA2 an attractive therapeutic target for SMARCA4-mutant tumor types, motivating multiple groups to generate SMARCA2 small molecule inhibitors or degraders." (PMID 33144586, 2020). "Whole-exome sequencing (WES) was performed on a single tumour with retained SMARCA4/SMARCA2 expression (ID 23)." (PMID 31844183, 2020). "In the one SMARCA4 wild-type tumor (IGR-03) which showed concomitant ARID1A and ARID1B mutations, SMARCA2 expression was higher at the mRNA level (real-time RT-PCR) than in SMARCA4 mutated samples, and interpreted as ambiguous/low at the protein level (IHC)." (PMID 32575483, 2020). "SMARCA2 promotes pancreatic tumorigenesis via JAK2/STAT3 signaling in vitro and in vivo, with increased SMARCA2 correlating to advanced tumor stage and poor prognosis in human patients." (PMID 31238554, 2019). "A variety of neoplasms have been discovered to have genomic alterations and loss of immunohistochemical (IHC) expression of chromatin remodelers ARID1A (BAF250A), SMARCA2 (BRM), SMARCA4 (BRG1), and SMARCB1 (INI1)." (PMID 31093468, 2018). "Taken together, these data suggest that a reduced level of SMARCA2 expression confers a selective advantage for many types of tumor cells." (PMID 29391527, 2018). "First we compared the levels of SMARCA4 and SMARCA2 transcripts in normal tissue with respect to tumor tissue in different types of tumors." (PMID 29391527, 2018). "A similar analysis for SMARCA2 showed that its expression was reduced in 104 out of the 132 tumor datasets selected." (PMID 29391527, 2018). "In contrast to SMARCA4, SMARCA2 expression was strongly downregulated in most cancer types, which is consistent with a role as tumor suppressor of this protein." (PMID 29391527, 2018). "A variety of neoplasms have been discovered to have genomic alterations (GAs) and loss of immunohistochemical (IHC) expression of chromatin remodelers ARID1A (BAF250A), SMARCA2 (BRM), SMARCA4 (BRG1), and SMARCB1 (INI1)." (PMID 31093468, 2018). "Since this initial discovery in the mid-1990s, two other SWI/SNF subunits have emerged as potential tumor suppressors: Brahma (BRM, SMARCA2) and Brahma Related Gene 1 (BRG1)." (PMID 27486753, 2016). "SMARCA2, the other ATPase subunit of the SWI/SNF complex, is also a bona fide tumor suppressor with frequent loss of expression via epigenetic silencing and more recently, mutational inactivation." (PMID 24622842, 2014). "Tumor-specific mutations in the following SMARCs are especially common: SMARCB1/SNF5, SMARCA2/BRM, and SMARCA4/BRG1." (PMID 24622842, 2014). "In response to the presence of rhabdoid cells in the tumor, further immunohistochemical studies were conducted to investigate the SWI/SNF chromatin remodeling complex, exhibiting deficiency in SMARCA2 (BRM) while maintaining proficiency in SMARCA4 (BRG1) and SMARCB1(INII)." (PMID 40012963, 2025). "Cell proliferation and DNA repair are critical determinants of tumor cell response to radiotherapy, and the involvement of SMARCA2 may influence this response." (PMID 40530955, 2025). "SMARCA2/4 dual-targeting PROTAC degraders that effectively inhibit tumor cell proliferation." (PMID 39697230, 2024). "When ACBI2 was dosed orally in a SMARCA2-sensitive mouse xenograft model, almost complete degradation of SMARCA2 was achieved although this was associated with tumour stasis rather than the hoped-for regression." (PMID 36720862, 2023).
tumor (continued). "An important gene, BRM (Brahma homolog; also known as SWI/SNF-related, matrix-associated, actin-dependent regulator of chromatin subfamily A member 2 or SMARCA2), has been identified as a promising new target in promoting tumor suppression." (PMID 37631312, 2023). "Unlike SMARCA4, its paralog SMARCA2 is not frequently mutated in cancers but rather is epigenetically silenced across numerous tumor types and cancer cell lines." (PMID 37093326, 2023). "Therefore, SMARCA2 is an attractive target to inhibit in SMARCA4-mutant cancers, utilising the enhanced reliance of tumour cells on BRM to completely prevent activity of the SWI/SNF chromatin remodeling complex and inhibit cancer cell growth." (PMID 37433987, 2023). "Overexpression of SMARCA2 has been shown in BC tumors compared to normal breast tissue and knockdown of the gene in triple-negative BC cell lines reduced tumor formation and growth, supporting a tumor-promoting function." (PMID 36901898, 2023). "At the same time, SMARCA2—shows a negative association with tumor de-differentiation status, regardless of the tumor type." (PMID 36674511, 2023). "Furthermore, recently developed ACBI2 preferentially degrades SMARCA2 and induces lung cancer tumor growth inhibition." (PMID 37093326, 2023). "In addition to the SMARCA4 mutation and retained SMARCA4 expression, the primary tumor in this study also displayed partial loss of SMARCB1 and SMARCA2 expression." (PMID 38201285, 2023). "In order to address whether the tumor growth inhibition observed in SMARCA4mut models was due to a tumor cell autonomous effect of SMARCA2 degradation, we evaluated A947 administration in the SMARCA4wt Calu-6 xenograft model." (PMID 36357397, 2022). "For example, tumors with rhabdoid features are aggressive and of high grade due to the dedifferentiation from a normal cell or low-grade tumor, induced by dual deficiency in SMARCA4 and SMARCA2, but an effective therapy to improve the outcome is still being investigated." (PMID 34440689, 2021). "Recent studies reported that the absence of SMARCA2 is equally necessary for the survival of SMARCA4-deficient tumor cells." (PMID 34440689, 2021). "Baseline genomic alterations in circulating tumor DNA, including SMARCA2, MSH6, APC signaling pathway, and Wnt signaling pathway, might be associated with the risk of HPD." (PMID 34858840, 2021). "However, SMARCA4 also has tumor suppressor activities in solid tumors, similarly to SMARCA2, which is generally classified as a tumor suppressor." (PMID 34298819, 2021). "In their computational meta‐analysis, Jose et al61 demonstrated that high SMARCA4 expression was associated with aggressive tumours, while high SMARCA2 expression was related to benign differentiated tumours, suggesting that SMARCA4 and SMARCA2 play opposite roles in cancers, including HCC." (PMID 32162380, 2020). "Imbalances between both complexes can be due to overexpression of EZH2 in undifferentiated cancers, but most commonly occur in cancers by mutations of members of the SWI/SNF complex, such as ARID1A and SMARCA4 that together with SMARCA2 is the ATPase subunit of this tumor-suppressing complex." (PMID 33230143, 2020). "SMARCA2 is not frequently mutated in tumours, but it is silenced in numerous cancer cell lines and primary tumours." (PMID 32162380, 2020). "Given that 5/44 SCCOHT retained some degree of SMARCA4 expression, we explored whether these SMARCA4-positive tumours may demonstrate other SWI/SNF alterations, in particular, loss of the other closely related catalytic domain, SMARCA2." (PMID 31844183, 2020). "Both SMARCA2 and SMARCA4 are tumor suppressors and mutations are frequently found in cancers, which may suggest an additional link between FANCA mutations and cancer predisposition." (PMID 31461451, 2019). "Further, our data highlight SMARCA4 as a universal vulnerability of SMARCA2-deficient cancer cells, irrespective of the tumor type." (PMID 31406271, 2019).
tumor (continued). "Tumor collections were ranked according to the SMARCA4 or SMARCA2 mRNA levels (RNA-seq data)." (PMID 29391527, 2018). "Several experimental data support a role of SMARCA2 as a tumor suppressor." (PMID 29391527, 2018). "SMARCA2 is not frequently mutated in tumors but gene silencing in tumor cell lines has been reported." (PMID 29391527, 2018). "The loss of BRM/SMARCA2 may have contributed to the epithelial-mesenchymal transition-driven transformation and, together with neuroendocrine differentiation, may have played a role in the tumor’s aggressiveness." (PMID 40989881, 2025). "Since SMARCA4 is generally regarded as a tumor suppressor gene and SMARCA4 mutations are thought to be involved in cancer progression, SMARCA2 targeting and the induction of cell death using the concept of synthetic lethality may be considered in the treatment of SMARCA4-mutated cancers." (PMID 38610978, 2024). "In addition to pivotal driver and tumor-suppressor mutations, several mutations were detected in some cancer genes associated with chromatin remodeling and RNA splicing, including SMARCA4 and SMARCA2 (SWI/SNF chromatin-remodeling factor genes)." (PMID 38102134, 2023). "In addition to STAT3, these included SMARCA2, a tumor suppressor involved in various cancers, SOCS1, a STAT-inhibitor, DNMT3A, with known somatic mutations in the context of clonal hematopoiesis and PPP3CA encoding calcineurin-A, involved in T-cell receptor signaling." (PMID 34874980, 2021). "Mutations of SMARCA2 are rarely observed but gene silencing related to epigenetic regulation in tumor has been reported, which is in line with strong hypermethylation observed in our Fusobacterium-enriched HNSCC tumor tissues when compared to Fusobacterium-low tumor tissues." (PMID 33218162, 2020). "Simcere has reported the SMARCA2 degrader ZM‐0011 (SCR‐9140), which significantly reduces intra‐tumoural SMARCA2 levels and suppresses tumour growth in mouse models, with a favourable tolerability profile." (PMID 41537447, 2026). "49,50 Our in vivo assessments with the orallybioavailable SMARCA2/4 PROTAC degrader, AU-24118, demonstrated a favorabletolerability profile alongside significant anti-tumor efficacy in multiple SCLC-Pand MM preclinical models." (PMID 39029462, 2024). "Immunostaining revealed that BRG1 (SMARCA4) expression was lost in the tumor cells, whereas INI1 (SMARCB1) and BRM (SMARCA2) proteins were retained." (PMID 38923369, 2024). "ACBI-1 is a PROTAC technology-based BAF ATPase subunit SMARCA2 and SMARCA4 degradant, is also a PBAF member PBRM1 degradant, and can effectively inhibit the proliferation of tumor cells." (PMID 39697230, 2024). "Our in vivo assessments with the first-in-class orally bioavailable SMARCA2/4 PROTAC degrader, AU-24118, demonstrated a favorable tolerability profile alongside significant anti-tumor efficacy in multiple SCLC-P and MM preclinical models." (PMID 38328238, 2024). "In cancer, both SMARCA2 and SMARCA4 have emerged as critical tumor suppressors, although several reports unveil their oncogenic potential." (PMID 36674511, 2023). "We went on to test ACBI2 in vivo and observed dose-dependent SMARCA2 degradation in NCI-H1568 and A549 engrafted tumour bearing mice following short-term treatment." (PMID 36216795, 2022). "The SMARCA2 (also known as BRAHMA, BRM) gene is involved in chromatin remodeling processes and is considered a tumor suppressor gene that is very often downregulated in various cancers." (PMID 34874980, 2021). "KAT2A, SP140 and BRD9 protein expression was higher in tumor tissues, and SMARCA2, BRPF3, KAT2B and EP300 protein expression was lower in the tumor tissues." (PMID 34149798, 2021). "In GSTM3-inhibited T98G cells, upregulated genes SMARCA2 and SEPT9 were found to suppress tumor markers." (PMID 34209254, 2021). "Aberrant SMARCA2 expression was most frequently found in EBV+ tumors (p < 0.001), advanced tumor stages (p = 0.019), and patients with positive lymph nodes (p = 0.043)." (PMID 34359794, 2021).